NLRP3 (NLR family pyrin domain containing 3)
Diseases named in the same sentence as NLRP3 in open-access papers (continued):
Sharing a sentence is not in itself a finding about the gene and the disease.
renal fibrosis (continued). "We demonstrated that TFNAs@PLT could reduce inflammation-mediated pyroptosis and apoptosis via Caspase-3/GSDME and NLRP3-mediated Caspase-1/IL-1β pathways in AKI, while also alleviating renal fibrosis through NLRP3/Caspase-1 and TNF-α/NF-κB pathways in CKD." (PMID 41355960, 2026). "There is a certain relationship between the NLRP3 inflammasome and renal fibrosis." (PMID 41394140, 2025). "Similarly, we revealed that the expression of NLRP3 was increased during the onset of renal fibrosis but decreased after hirudin treatment." (PMID 40298655, 2025). "Elevated neutrophils in DKD could drive the synthesis of inflammasome NLRP3, stimulate the release of inflammatory cytokines, which promote renal fibrosis, glomerular and tubular damage." (PMID 41367911, 2025). "It has been documented that HIF-1α-BNIP3-mediated mitophagy mitigates renal fibrosis by inhibiting the activation of the NLRP3 inflammasome, and BNIP3-mediated mitophagy also exerts a protective effect on neuroinflammation by suppressing the assembly of the NLRP3 inflammasome." (PMID 40242759, 2025). "A recent study suggested that TGF-β-mediated NLRP3 inflammasome activation may trigger the release of high-mobility group box 1, thereby exacerbating the pathological progression of Ang II-induced renal fibrosis in hypertensive nephropathy." (PMID 40841164, 2025). "p-STAT3 and NLRP3 levels were associated with the activation or inhibition of ferroptosis, suggesting that the effect of hirudin on renal fibrosis by inhibiting ferroptosis may be related to the STAT3/NLRP3 signaling pathway." (PMID 40298655, 2025). "Therefore, NLRP3 deficiency attenuates TGF-β1-triggered EMT and renal fibrosis in vitro and in diabetic mouse models." (PMID 40568564, 2025). "Hirudin improved renal fibrosis by inhibiting ferroptosis via the STAT3/NLRP3 signaling pathway." (PMID 40298655, 2025). "The NLRP3 inflammasome drives renal fibrosis by activating T cells via the IL-23/IL-17 axis." (PMID 41357229, 2025). "BPS may alleviate the inflammatory response and the process of renal fibrosis in db/db mice by regulating NLRP3 inflammasome." (PMID 41394140, 2025). "In conclusion, these studies indicate that the NLRP3 inflammasome may affect renal fibrosis via the intestine-renal axis and the interaction between intestinal microbiota, presenting additional potential avenues for CKD treatment." (PMID 40841164, 2025). "uncovered that Bi Xie Fen Qing Yin decoction could inhibit NLRP3 inflammasome activation by modulating intestinal flora, consequently impeding renal fibrosis in the hyperuricemic nephropathy model." (PMID 40841164, 2025). "IL-22 inhibits NLRP3 activation, reduces albuminuria, and attenuates renal fibrosis." (PMID 41357229, 2025). "Meanwhile, there is a study that argued that inhibiting the activation of NLRP3 has a certain effect on the treatment of renal fibrosis, and this function may be related to antioxidants." (PMID 39473254, 2025). "In patients with renal fibrosis, the expression levels of NLRP3 and Caspase-1 are significantly up-regulated, suggesting that the NLRP3 inflammasome may be activated and involved in regulating renal fibrosis." (PMID 38820434, 2024). "Pyroptosis in macrophages interacted with TECs regulating the progression of renal fibrosis, and circACTR2 regulated macrophage inflammation, epithelial–mesenchymal transition, and the development of renal fibrosis by activating NLRP3 inflammasome via sponging miR-561." (PMID 39000237, 2024). "This suggests that macrophage-derived exosomes under high glucose conditions exacerbate the inflammatory response and activate the NLRP3 inflammasome, leading to abnormal proliferation of mesangial cells, excessive extracellular matrix accumulation, and accelerated renal fibrosis." (PMID 39104818, 2024).
renal fibrosis (continued). "Pyrroloquinoline quinone (PQQ), a naturally occurring bioactive, ameliorated renal fibrosis in DKD by inhibiting oxidative stress, phosphorylated NF-κB, the loss of mitochondrial transmembrane potential, and the NF-κB /NLRP3 pyroptosis pathway in DKD mice and high-glucose-treated HK-2 cells." (PMID 39000237, 2024). "However, in UUO mice and hypoxia-induced HK-2 cells, knockdown of BNIP3 aggravated mitochondrial structural damage, decreased mitophagy and increased mtROS expression, which further enhanced NLRP3-mediated inflammation and aggravated renal fibrosis after UUO." (PMID 38680884, 2024). "The nucleotide-binding domain, leucine-rich-containing family, pyrin domain-containing-3 (NLRP3) inflammasome is another pathway that may mediate TMAO-induced renal fibrosis." (PMID 39180015, 2024). "Interestingly, NLRP3 appears to have a protective effect on renal fibrosis, as evidenced by conditions where it is knocked down or inhibited." (PMID 38732005, 2024). "Notably, the depletion of NLRP3 significantly alleviated the severity of renal fibrosis in mouse models." (PMID 38785272, 2024). "In our study, we found that mitoTEMPO, a mitochondrial antioxidant agent, and MCC950, a specific NLRP3 inhibitor, could downregulate the expression of the NLRP3 inflammasome and alleviate renal fibrosis in the siBNIP3+hypoxia group in HK-2 cells." (PMID 36928344, 2023). "In addition to mediating the inflammatory response, the NLRP3 inflammasome is also involved in pyroptosis, mitochondrial regulation, and the transformation and proliferation of myofibroblasts during renal fibrosis." (PMID 37500614, 2023). "Many studies have shown that elevated levels of NLRP3 and caspase-1 are associated with renal fibrosis in CKD patients, indicating that the NLRP3 inflammasome may participate in renal fibrosis." (PMID 36928344, 2023). "Recent evidence revealed that complanatoside A inhibits NOX4-mediated NLRP3 inflammasome activation and oxidative stress, indicating that complanatoside A could be used to treat renal fibrosis." (PMID 37500614, 2023). "In summary, the NLRP3 inflammasome is involved in mitochondrial homeostasis and renal fibrosis." (PMID 36928344, 2023). "NLRP3 is associated with renal fibrosis after UUO, whereas IL-1β, IL-18, and caspase-1 are not necessary for these pathways." (PMID 37685978, 2023). "Our study for the first time adopted the intragastric injection of PS in UUO-induced renal fibrosis and found that PS could alleviate renal inflammation and fibrosis in mice by inhibiting the NLRP3 pathway." (PMID 37685978, 2023). "The activation of the NLRP3 inflammasome promotes the activation of inflammatory caspases (caspase-1)-dependent pro-inflammatory hormones IL-1β and IL-18, which, in turn, promotes renal fibrosis." (PMID 36421424, 2022). "On the other hand, NLRP3 inflammasome inhibition with MCC950 could relieve cisplatin-induced renal fibrosis by diminished oxidative stress and inflammation." (PMID 36175910, 2022). "Based on previous research, we hypothesized that TLYS might protect renal functions against renal fibrosis via NLRP3 inflammasome-induced pyroptosis." (PMID 35873572, 2022). "It is further revealed that selective inhibition of NLRP3 inflammasome could attenuate cisplatin-induced renal fibrosis with diminished oxidative stress and inflammation." (PMID 36175910, 2022). "NLRP3 plays an important role in the activation of renal fibrosis." (PMID 35185542, 2021). "Furthermore, several studies have suggested NLRP3 inhibition to be a novel treatment target with a possible effect on renal function, renal fibrosis, hypertension, atherosclerosis, and DM." (PMID 33670423, 2021). "Furthermore, NLRP3-positive tubules were correlated with renal fibrosis (r = 0.8162; p < 0.0001) and inflammatory infiltration (r = 07956; p < 0.0001), respectively." (PMID 34716316, 2021). "Knocking down Aim2 and NLRP3 can alleviate renal fibrosis, inflammation, and injury." (PMID 34017258, 2021).
renal fibrosis (continued). "It was also found that CP-456,773, a specific inhibitor of NLRP3, could delay the progression of mouse renal fibrosis owing to its early-stage inhibitory effect." (PMID 34007404, 2021). "Targeting the NF-κB and/or the NLRP3 inflammasome systems may represent a new strategy in the effort to prevent the progression of renal fibrosis and, in particular, the AKI-CKD transition." (PMID 34305624, 2021). "Autophagy/NLRP3 inflammasome is an important target in the treatment of renal fibrosis." (PMID 34884572, 2021). "Collectively, these results suggest that TGF-beta-mediated NLRP3 inflammasome activation may cause the release of HMGB1 and an increase in Gasdermin D cleavage in NRK-52E, thereby contributing to renal fibrosis in Ang II-induced CKD." (PMID 32117956, 2020). "XIAP functions as a caspase inhibitor, the expression of which is also decreased by the grape seeds with antioxidant activity, suggesting that XIAP may be involved in the NLRP3 inflammasome activation and renal fibrosis by regulating ROS." (PMID 33390969, 2020). "So, it could be inferred that H2S alleviates renal fibrosis in response to UUO by suppressing macrophage infiltration through inhibition of NLRP3 inflammasome via NF-κB and IL-4/STAT6 signaling pathways, which needed to be further proven 57-59." (PMID 33110394, 2020). "In the present study, we aimed to investigate whether SSR could alleviate renal fibrosis by regulating NLRP3 inflammasome and Sirt1/Smad3 deacetylation pathway." (PMID 31118021, 2019). "Therefore, the role and regulation of the NLRP3 inflammasome during renal fibrosis are here reviewed." (PMID 32039201, 2019). "Renal fibrosis significantly decreased after UUO in the kidney of NLRP3 KO mice." (PMID 30483252, 2018). "And the mechanism may be related to the inhibition of NLRP3 inflammasome and early renal fibrosis growth factor TGF-β1 and FN induced by EMT." (PMID 28182085, 2017). "Our characterization of the NLRP3 inflammasome/mitochondrial dysfunction axis may offer new insights into the prevention of renal fibrosis in CKD." (PMID 28348462, 2017). "Thus, DIO’s therapeutic efficacy in DN may arise from its concurrent targeting of NLRP3-driven renal fibrosis and gut barrier preservation, highlighting the interconnectedness of mucosal immunity and chronic kidney disease pathogenesis." (PMID 40458807, 2025). "Moreover, NLRP3 deletion ameliorates renal fibrosis by inhibiting mitochondrial dysfunction." (PMID 40298655, 2025). "The long-term effects of the ATP/P2X7R/NLRP3 pathway on renal fibrosis remain unclear." (PMID 40520155, 2025). "Notably, a correlation exists between the NLRP3 inflammasome and renal fibrosis." (PMID 41394140, 2025). "Additionally, allopurinol inhibits NLRP3/NF-κB inflammasome activation and reduces renal fibrosis." (PMID 38570748, 2024). "Notably, activated NLRP3 inflammasome contributed to the generation of pro-fibrotic factors, and the secretion of IL-1β/18 was an initial and vital occurrence of inflammatory responses in renal fibrosis." (PMID 37500614, 2023). "Furthermore, through the NLRP3/caspase-1/IL-1β pathway, IL-22 can reverse the overexpression of fibronectin, collagen IV, and extracellular matrix in mouse renal glomerular mesangial cells, thereby ameliorating renal fibrosis and proteinuria excretion in DN." (PMID 36776877, 2023). "Moreover, recent evidence showed that phloretin could effectively attenuate hyperuricemia-induced CKD and renal fibrosis by inhibiting NLRP3 inflammasome activation and uric acid reabsorption." (PMID 37500614, 2023). "Interestingly, the phosphoinositide 3-kinase (PI3K) inhibitor 3-methyladenine (3-MA), which inhibits autophagy, was found to prevent renal injury onset and reduce renal fibrosis, macrophage infiltration, and the production of NLRP3 and IL-1β in injured kidneys." (PMID 38041694, 2023).
renal fibrosis (continued). "Blockage of NLRP3 attenuates macrophage infiltration, M1 polarization, decrease in gene expression of connexins, TGF-β, connective tissue growth factor and α-smooth muscle actin, reduction of extracellular matrix deposition, and prevents renal fibrosis and loss of renal function." (PMID 32660446, 2020). "Therefore, determining whether NLRP3 inflammasomes play a crucial role in TGF-beta-mediated renal fibrosis is required before effective therapeutic targets can be identified." (PMID 32117956, 2020). "TLR2 and TLR4, as well as the NLRP3 inflammasome, seem to be activated during the development of tubulointerstitial inflammation in mice receiving dietary adenine overload, which were protected from renal fibrosis when genes coding for these molecules were deleted." (PMID 31649546, 2019). "Therefore, the inhibition of NLRP3 inflammasome and activation of Sirt1 could be attractive targets to ameliorate renal fibrosis." (PMID 31118021, 2019). "Increasing evidence strongly indicates that the expression levels of NLRP3 and caspase-1 are significantly elevated in the kidneys of CKD or fibrosis patients, suggesting that the NLRP3 inflammasome may be activated and involved in the regulation of renal fibrosis." (PMID 32039201, 2019). "Nlrp3 deficiency did not affect renal fibrosis or inflammation." (PMID 24454932, 2014). "We further investigated whether Nlrp3 influenced the progression of renal fibrosis." (PMID 24454932, 2014). "This was further confirmed by pharmacological inhibition in a mouse model of UUO in which blockade of NLRP3 inhibited TGF-β/Smad3 signaling, MMT, and progressive renal fibrosis." (PMID 42157945, 2026). "Mechanistically, we uncovered that NLRP3 directly bound TGF-β receptors II and I to trigger the activation of TGF-β/Smad3 signaling and progressive renal fibrosis via the macrophage-myofibroblast transition (MMT) process." (PMID 42157945, 2026). "Studies have demonstrated a significant upregulation of NLRP3 inflammasome expression in UUO-induced kidney disease, which correlates positively with renal fibrosis severity." (PMID 40841164, 2025). "Dexmedetomidine alleviates LPS-induced renal injury by inhibiting myofibroblast activation, NLRP3 inflammasome formation, and cell necrosis, suppressing EMT, and reducing renal fibrosis." (PMID 41041277, 2025). "As an NLRP3 inflammasome inhibitor, glibenclamide has been shown to attenuate adenine-induced CKD and renal fibrosis in rats." (PMID 41357229, 2025). "P2X7 receptor (P2X7R) is reported involved in renal fibrosis and the activation of NOD-like receptor protein 3 (NLRP3) inflammasome." (PMID 40520155, 2025). "The study demonstrated that hirudin effectively reduces ferroptosis and renal fibrosis in UUO rats and RSL3-induced HK-2 cells, while decreasing protein levels related to the STAT3/NLRP3 signaling pathway." (PMID 40298655, 2025). "Taken together, PINK1-Parkin-mediated mitophagy ameliorated renal fibrosis and alleviated the development of hyperuricemia -induced CKD by reducing mtROS and NLRP3 mediated inflammation." (PMID 38680884, 2024). "Of note, TGF-β1 stimulated the expression of α-SMA and NLRP3 inflammasome in renal tubule epithelial cells, thus promoting epithelial-to-mesenchymal transition (EMT) and renal fibrosis." (PMID 37500614, 2023). "BNIP3 deficiency increased the production of mitochondrial ROS, the NLRP3 inflammasome, and αSMA and TGFβ1 expression, indicating the protective role of BNIP3-mediated mitophagy in renal fibrosis." (PMID 36928344, 2023). "Our data are in line with other research that identified CHR-mediated inhibition of pro-fibrotic pathways in rat myocardial injury, renal fibrosis and osteoarthritis, by reducing TGF-β1/Smad3, p38, Erk1/2, MMP2 and PERK/TXNIP/NLRP3 signalling." (PMID 38169923, 2023).
renal fibrosis (continued). "Owing to modulation of the GPx-1/NLRP3/Caspase-1 pathway, Se@BSA NPs ameliorated the renal function of IRI-AKI mice in a dose-dependent manner and dramatically arrested the development of renal fibrosis after AKI." (PMID 35664065, 2022). "Autophagy can also exhibit its effects on the process of renal fibrosis by regulating the TGF-β1 and NLRP3 inflammatory vesicle signaling pathways." (PMID 36105212, 2022). "NLRP3 knockdown downregulates the expression of TGF-β1 and blocks the EMT process in high glucose-induced renal fibrosis." (PMID 32508821, 2020). "MCC950, a selective inhibitor of NLRP3 andM920, a broad specificity caspase inhibitor, improved renal function, GBM thickening, podocyte injury, renal fibrosis, and NLRP3-dependent markers in db/db mice." (PMID 32471207, 2020). "Therefore, the NLRP3 inflammasome pathway may serve as a valuable prophylactic and therapeutic target for the treatment of renal fibrosis and may also provide a potential target for minimizing the severe clinical complications observed in CKD patients with advanced renal impairment." (PMID 32039201, 2019). "Here we found that deletion of RIPK3 or MLKL alleviated the NLRP3 inflammasome activation and IL-1β release in kidney after IRI corresponding with the reduction of renal fibrosis." (PMID 30158627, 2018). "Previous UUO experiments have revealed that renal fibrosis, inflammation and mitochondrial dysfunction were attenuated in the UUO-treated kidney of NLRP3 KO mice." (PMID 30483252, 2018). "Based on these findings, we hypothesized that hirudin might ameliorate renal fibrosis by alleviating ferroptosis, and that this therapeutic effect could be mediated through the STAT3/NLRP3 signaling pathway." (PMID 40298655, 2025). "Additionally, TMAO induces oxidative stress and activates NLRP3 inflammasomes through the MAPK pathway, thereby impairing renal function and inducing renal fibrosis." (PMID 40777990, 2025). "In summary, this study reveals that BPS can improve kidney damage and renal fibrosis in db/db mice with DN, and its mechanism may be related to reduced apoptosis, inhibiting inflammation, reducing ECM deposition, and regulating the NLRP3 inflammasome." (PMID 41394140, 2025). "In a cisplatin-induced renal fibrosis model, MCC950 was found to significantly alleviate renal dysfunction, tubular injury, interstitial collagen deposition, and profibrotic factor expression by inhibiting NLRP3 inflammasome activation." (PMID 40841164, 2025). "Additionally, the Huangkui capsule counteracts tubular epithelial-to-mesenchymal transition (EMT) induced by NLRP3 inflammatory vesicle activation through the TLR4/NF-κB signaling pathway, thus contributing to the alleviation of renal fibrosis." (PMID 39104818, 2024). "NLRP3 inflammasome-mediated pyroptosis performs significant regulatory functions in multiple kidney diseases such as unilateral ureteral occlusion (UUO), diabetic nephropathy (DN), obstructive nephropathy, lupus nephritis, and renal fibrosis." (PMID 37500614, 2023). "Likewise, activation of the NLR family pyrin domain containing 3 (NLRP3) and toll-like receptor 9 (TLR9) regulate macrophage polarization and renal fibrosis in different preclinical models." (PMID 38201227, 2023). "It was reported that NLRP3 deletion could reverse the damage to mitochondria in the context of UUO and mitigate renal fibrosis." (PMID 36928344, 2023). "Furthermore, renal fibrosis was attenuated by MitoTEMPO and MCC950, indicating that HIF1α-BNIP3-mediated mitophagy protected against renal fibrosis by regulating the NLRP3 inflammasome." (PMID 36928344, 2023). "The absence of NLRP3 in animal disease models contributes to lowered expression of pro-inflammatory factors and improved renal fibrosis." (PMID 36601125, 2022).